CDKN2A (cyclin dependent kinase inhibitor 2A)
Diseases named in the same sentence as CDKN2A in open-access papers (continued):
Sharing a sentence is not in itself a finding about the gene and the disease.
atherosclerosis (continued). "Another study demonstrated that deletion of the targeted 9p21.3 risk locus of orthologous ANRIL interval in mice reduced the expression of CDKN2A and CDKN2B in the heart and led to excessive proliferation of vascular cells that contribute to the development of atherosclerosis." (PMID 38149798, 2024). "Markedly decreased expression of CDKN2A and CDKN2B was reported in mutant mice and doubling of the proliferative capacity of mutant aortic smooth muscle cells in culture was detected, a cellular phenotype relevant to atherosclerosis." (PMID 35653368, 2022). "The expression of ANRIL transcripts (EU741058 and NR_003529) in atherosclerotic plaque tissue was directly correlated with severity of atherosclerosis; however, no such correlation was found in CDKN2A, CDKN2B and MTAP." (PMID 21698238, 2011). "Therefore, CDKN2A, GLS, and MTF1 possess therapeutic potential for atherosclerosis." (PMID 39519014, 2024). "CAD risk alleles were all associated with reduced ANRIL expression, up to 1.9-fold, suggesting that expression of ANRIL, rather than CDKN2A or CDKN2B, might mediate atherosclerosis susceptibility." (PMID 20386740, 2010).
head and neck cancer (75 papers, 2008 to 2025). A primary or metastatic malignant neoplasm affecting the head and neck. "In this work, we used cancer cell lines from lung, breast, thyroid, and head and neck cancers that carry nonsense mutations or CDKN2A deletions." (PMID 34454516, 2021). "Frequent HPV-independent overexpression of p16Ink4a in head and neck carcinomas has been explained by mutation or amplification of CDKN2A or by mutations in RB1 or histone H3 lysine 36 methyltransferase genes." (PMID 32542012, 2020). "CDKN2A is rarely altered in HPV-positive (0%) compared with HPV-negative head and neck cancers (25% mutation rate, frequent alterations in 9p21.3 chromosomal region containing the CDKN2A gene)." (PMID 28771191, 2017). "Given the role of CDKN2A in early cell cycle regulation and frequent alterations in head and neck cancers, its presence in OED is biologically plausible." (PMID 41463200, 2025). "Our previous studies in head and neck cancer identified copy number alterations in CDKN2A and/or CDK4 as predictive biomarkers and molecular correlates of response to abemaciclib." (PMID 40753072, 2025). "Several studies of head and neck cancer have identified promoter methylation of CDKN2A (p16), DAP kinase (DAPK), and DNA repair genes MGMT and MLH110,11." (PMID 38589501, 2024). "Recent studies described the germline variants of CDKN2A, RECQL4, and SDHB in the DNA repair genes associated with a high risk of head and neck cancer in young patients." (PMID 36552033, 2022). "MCM7 and CDKN2A (p16) were proposed as biomarkers for HPV-positive head and neck cancer, while CDKN2A (p16) alone was suggested as a marker in HPV-infected oropharyngeal cancers with favourable prognosis." (PMID 18349847, 2008). "In addition, it was also found that a CDKN2A/p16 (+) status in head and neck cancer was strongly predictive of poorly differentiated tumors." (PMID 33968767, 2021). "CDKN2A methylation positively correlates with p16INK4A/p14ARF expression in head and neck cancer." (PMID 32328088, 2020). "Methylated CDKN2A may therefore be a useful marker in diagnosis and prognosis for head and neck cancer." (PMID 31712935, 2020). "In head and neck cancer, aberrant promoter methylation has been found in a wide variety of genes including p14ARF, p15, p15INK4B, p16, p16INK4A, ATM, DCC, DAPK, MINT1, MINT2, MINT27, MINT31, RARbeta, CDH1, cyclin A1, cytoglobin, RASSF1A, LHX6, MLH1, MGMT, and CDKN2A." (PMID 22645613, 2012). "However, in the MSK-IMPACT cohort of our study the PD1/PD-L1 inhibitors seem to improve the clinical outcome of CDKN2A-MUT patients with NSCLC or head and neck cancer, treated by ICIs, in despite of CDKN2A ALT being found to be a risk factor of survival in the MSK-MetTropism and TCGA cohorts." (PMID 38822443, 2024). "However, other mutations, such as Notch1, CDKN2A, FAT1, PTEN HRAS, and PI3KCA, frequently occurring in head and neck cancer, may influence metastatic events." (PMID 37894373, 2023). "However, according to these results, FGFR3/4 and CDKN2A/B could be biomarker candidates to be studied on lung and head and neck cancers." (PMID 29544535, 2018). "Thus, in addition to CDKN2A, TβR-I gene could be added to the list of cancer genes that must be tested for methylation-based detection of head and neck cancer." (PMID 20111589, 2009). "We conclude that CCND1, AXL, CDKN2A, TERT, and EZH2 are the hub genes involved in cisplatin resistance in head and neck cancer that have significant mRNA expression and effect on overall survival." (PMID 36715825, 2023).
head and neck cancer (continued). "The epigenetic alterations of CDKN2A (p16; located at 9p21), CDH1 (16q22.1), FHIT (3p14.2), RAR-β (3p24.2), and ATM (11q22.3) have been found to be related to clinical prognosis in cancer of the head and neck." (PMID 24782031, 2014). "This hypomethylated set of genes included many genes that have previously been shown to be methylated in head and neck cancer, including RASSF1, CHFR, RUNX3, APC, and CDKN2A (p16)." (PMID 23358896, 2013). "We compared DNA methylation and ARF/INK4a RNA expression levels for the CDKN2A locus using the Illumina HumanMethylation27 beadchip and RT‐PCR in 43 LXSCC tumor samples collected from a prospective study of head and neck cancer patients treated at Montefiore Medical Center (MMC)." (PMID 28102032, 2017). "In addition, promoter methylation of CDKN2A, MGMT, DAPK1, and CDH1 has been studied in relation to head and neck cancer survival." (PMID 19807915, 2009).
bladder cancer (73 papers, 1999 to 2025). "Of the 706 bladder cancer patients enrolled in the study, 37 (5.2%) carried a p.A148T variant in CDKN2A (OR = 1.5; 95% CI 1.04–2.24; p = 0.04)." (PMID 35478773, 2022). "The only common deletion concerns locus 9p21.3 which encompasses genes CDKN2A and CDKN2B encoding for tumor suppressors p14ARF and p15INK4b and occurs in 31.9% of bladder carcinomas." (PMID 35323317, 2022). "There was some nominal evidence that the CDKN2A p.A148T polymorphism reduced survival in the subgroup of bladder cancer patients under 60 years of age." (PMID 35478773, 2022). "Materials and Methods: We compared the allele frequencies of NOD2 c.3020insC and CDKN2A p.A148T allele in 706 patients with bladder cancer, 410 cases with kidney cancer against two control groups." (PMID 35478773, 2022). "Overexpression of CDKN2A is significantly observed in genomically unstable tumors associated with shorter progression-free survival in bladder cancer patients." (PMID 34885040, 2021). "Previous studies have demonstrated genomic alterations in CDKN2A in 20 to 60% of bladder carcinomas, which are associated with either RB1 deletions or E2F amplification." (PMID 34885040, 2021). "Pathway analysis of affymetrix data file shows upregulation of four genes ERBB2, DAPK1, FGFR3 and CDKN2A which have reference to prove their involvement in causing bladder cancer." (PMID 22276047, 2011). "To ensure that our original findings were not erroneous and indeed represented the actual frequency found in bladder and kidney cancer patients, we re-evaluated the frequency of the NOD2 c.3020insC allele and the p.A148T polymorphism in CDKN2A among 706 bladder cancer and 410 kidney cancer patients." (PMID 35478773, 2022). "Additionally, previous studies have suggested that CDKN2A loss could be predictive of immunotherapy response and progression, as well as prognostic value in bladder cancer." (PMID 39113632, 2024). "Uropathogenic E. coli infection induces de novo methyltransferase activity and DNMT1 expression causing increased methylation of CDKN2A exon 1 and downregulation of this tumor suppressor gene in uroepithelial cells, which may increase the risk of bladder cancer." (PMID 34394088, 2021). "In terms of the functional effect of the variant in CDKN2A (p16INK4A, D74A) on protein function, it is likely that this variant is significant, as mutation of aspartic acid 74, to asparagine has been identified in bladder carcinoma and esophageal squamous cell carcinoma." (PMID 27519597, 2016). "Encouragingly, 215 CDKN2A-MUT patients with bladder cancer after ICIs treatment had better OS than CDKN2A-WT patients in this study." (PMID 38822443, 2024). "Many studies have investigated the clinical-pathological and prognostic significance of CDKN2A gene in patients with bladder cancer." (PMID 35478773, 2022). "•In bladder cancers, FGFR3 SVs were significantly associated with CDKN2A/B and TERT alterations, and a lower TMB." (PMID 36462464, 2022). "They suggested that low CDKN2A expression was correlated with worse prognosis for progression-free survival and recurrence-free survival in Ta–T1 bladder cancer." (PMID 35478773, 2022). "The 9p21 deletion is one of the most frequently reported somatic CNAs in bladder cancer, and it covers the CDKN2A gene." (PMID 32012866, 2020).
bladder cancer (continued). "Genes reported to be epigenetically inactivated by hypermethylation in bladder cancer include p16INK4a, CDKN2A, RUNX3 or RASSF1, among others." (PMID 18087279, 2008). "Based on the cancer-specific hypermethylation of the CDKN2A exon 2 CpG island observed in colorectal and bladder cancers, we tested this downstream island instead." (PMID 17967182, 2007). "However, many studies have found that CDKN2A is related to poor prognosis in bladder cancer, pancreatic adenocarcinoma, hepatocellular carcinoma (HCC), and so on." (PMID 35429970, 2022). "The study revealed that the presence of the NOD2 c.3020insC variant and the CDKN2A p.A148T polymorphism did not influence bladder cancer survival." (PMID 35478773, 2022). "In summary, the results of this study indicate that neither the NOD2 c.3020insC variant or the CDKN2A p.A148T polymorphism are associated with the survival of bladder cancer patients regardless of age, cancer family history, smoking status and sex." (PMID 35478773, 2022). "In summary, using a series of bioinformatics and retrospective analyses, the present study identified a subset of seven genes (CDC20, CDKN2A, CTSV, FOXM1, KRT23, MAGEA6, and S100A9), which were significantly associated with progression and prognosis of bladder cancer." (PMID 34885040, 2021). "With the pathological variant where the two growth inhibitors p14ARF and p16INK4a are absent, this desired precedence might be compromised in favour of tumorigenesis, thus correlating with the observed CDKN2A gene deletion in bladder cancers." (PMID 29515890, 2018). "By using the partition test in the MDA cohort of 57 bladder cancer patients a similar cut-off for CDKN2A expression could be defined." (PMID 30258198, 2018). "The genetic alteration of CDKN2A is most common clinically relevant in the advanced bladder cancer." (PMID 27167196, 2016). "Interestingly, the findings from formalin fixed paraffin embedded samples were comparable to the plasma samples of invasive high grade bladder cancer patients for CDKN2A, MGMT and RASSF1A." (PMID 24790823, 2014). "In agreement with prior literature, significant copy number alterations involved deletion of CDKN2A/B, leading to cell cycle dysregulation, and focal amplifications in CCND1 and MDM2, which are well-documented events in bladder cancer." (PMID 41373802, 2025). "CDKN2A, CTSV and FOXM1 with 95.5% sensitivity and 100% specificity in predicting bladder cancer progression." (PMID 34885040, 2021). "The PPI network analysis of three databases identified the following subsets of DEGs, including CDC20, CDKN2A, CTSV, FOXM1, KRT23, MAGEA6, and S100A9, which were significantly upregulated in bladder cancer." (PMID 34885040, 2021). "The expression profile of CDC20, CDKN2A, CTSV, FOXM1, KRT23, MAGEA6, and S100A9 were significantly higher in bladder cancer specimens compared with normal bladder tissue in patients." (PMID 34885040, 2021). "Regarding CDKN2A and its interaction with MAGEA6 very little is known so far, moreover previous studies identified higher expression of MAGEA6 in early stage bladder cancer." (PMID 34885040, 2021). "CDKN2A and CDKN2B are located on chromosome 9p, and commonly deleted in bladder cancer, as well as other cancer types." (PMID 31857723, 2020).
bladder cancer (continued). "In human bladder cancer cells, selective depletion of DNMT1 with siRNA induced demethylation and reactivation of the silenced tumor-suppressor gene CDKN2A." (PMID 21999220, 2011). "Moreover, the co‐expression of ITGB3BP and cyclin‐dependent kinase inhibitor 2A (CDKN2A) is very common in human solid tumours, particularly in bladder cancer." (PMID 34953037, 2022). "It is noteworthy that the deletion of CDKN2A and CDKN2B, key regulators of Cdk4/6 expression, occurs in ~50% of bladder cancers, as this indicates that many MI-BC patients may be responsive to Cdk4/6 inhibitors." (PMID 30875757, 2019). "Furthermore, the study also revealed a three-panel gene set (CDKN2A, CTSV, and FOXM1) that can accurately predict tumor progression and suggested as potential prognostic biomarker(s) for bladder cancer, which could aid in clinical decision making." (PMID 34885040, 2021). "A total of seven genes, including CDKN2A, CDC20, CTSV, FOXM1, MAGEA6, KRT23, and S100A9 were confirmed with strong prognostic values in bladder cancer and validated by qRT-PCR conducted in various human bladder cancer cells representing stage-specific disease progression." (PMID 34885040, 2021).